RCL1 (RNA terminal phosphate cyclase like 1)
Description:
As part of the small subunit (SSU) processome, it plays a role in 40S-ribosomal-subunit biogenesis in the early pre-rRNA processing steps at sites A0, A1 and A2 that are required for proper maturation of the 18S RNA (By similarity). Activates BMS1 by promoting GDP/GTP exchange (By similarity). Does not have cyclase activity (By similarity).
Synonyms: RNAC; RPCL1
Tractability: Small molecule: a structure with a bound ligand is known. PROTAC: ubiquitination databases record sites on it; its protein half-life has been measured.
Gene: Protein-coding gene on chromosome 9 (4,792,944 to 4,885,917, forward strand). Ensembl gene ENSG00000120158.
Subcellular location: Nucleus, nucleolus
Subcellular location (Human Protein Atlas): Nucleoplasm
Pathways (Reactome):
Metabolism of RNA: Major pathway of rRNA processing in the nucleolus and cytosol; rRNA modification in the nucleus and cytosol
Gene Ontology:
Molecular function: protein binding; RNA endonuclease activity; catalytic activity
Biological process: ribosomal small subunit biogenesis; endonucleolytic cleavage in 5'-ETS of tricistronic rRNA transcript (SSU-rRNA, 5.8S rRNA, LSU-rRNA); endonucleolytic cleavage in ITS1 to separate SSU-rRNA from 5.8S rRNA and LSU-rRNA from tricistronic rRNA transcript (SSU-rRNA, 5.8S rRNA, LSU-rRNA); maturation of SSU-rRNA; ribosome biogenesis; RNA processing
Cellular component: small-subunit processome; nucleolus; nucleoplasm
Genetic constraint (gnomAD): Loss-of-function variants: 13 observed, 24.95 expected, observed/expected ratio (o/e) 0.52, 90% interval 0.34 to 0.83. The upper end of that interval is the gene's LOEUF score, 0.83, which puts it in group 3 of 6, group 1 being the genes least tolerant of losing a copy. Missense variants: 379 observed, 318.11 expected, observed/expected ratio (o/e) 1.19, 90% interval 1.1 to 1.3. Synonymous variants: 147 observed, 122.68 expected, observed/expected ratio (o/e) 1.2, 90% interval 1.05 to 1.37.
Homologues: Orthologues: chimpanzee RCL1 (99% identical), macaque RCL1 (99% identical), rabbit RCL1 (98% identical), guinea pig RCL1 (97% identical), mouse Rcl1 (97% identical), dog RCL1 (97% identical), tropical clawed frog rcl1 (81% identical), zebrafish rcl1 (75% identical), rat Rcl1 (61% identical), Drosophila melanogaster Rtc1 (54% identical), Caenorhabditis elegans ZK1127.5 (47% identical). Paralogues in human: RTCA (26% identical).
Diseases named in the same sentence as RCL1 in open-access papers:
RCL1 is named in the same sentence as 35 diseases in open-access papers, as found by Europe PMC text mining. Sharing a sentence is not in itself a finding about the gene and the disease. The quoted sentences say what the papers report.
depression (3 papers, 2019 to 2021). "A recent GS study focused on the identification of rare variants in families from an isolated population reported a missense p.Leu372Phe variant (rs115482041) in RCL1 segregating with depression in a multi-generation pedigree." (PMID 33597717, 2021). "Genetic analyses suggested new genes that might play a role in depression, for example RCL1 was identified as a novel candidate gene for depression and 44 new independent loci associated with depression were found in a large GWAS." (PMID 32367290, 2020). "Additionally, a rare missense variation in RCL1 was recently associated with depression." (PMID 31263560, 2019). "While RCL1 has not yet been reported in the context of psychotic symptoms, a rare missense variant in RCL1 has been linked to an increased risk of depression." (PMID 33597717, 2021).
hepatocellular carcinoma (3 papers, 2022 to 2025). A malignant tumor that arises from hepatocytes. "RCL1 encodes an endonuclease involved in processing pre‐rRNA and has recently been proposed as a novel tumor suppressor in hepatocellular carcinoma." (PMID 40561176, 2025). "Evidence suggests that RCL1 weakens hepatocellular carcinoma progression." (PMID 36246620, 2022). "Clinical implication data related to RCL1 level in Hepatocellular Carcinoma (HCC) samples were downloaded through TCGA, ICGC, GEO databases." (PMID 35264160, 2022).
breast carcinoma (2 papers, 2016 to 2022). "Previous studies have indicated that RCL1 could independently predict breast cancer prognosis and copy number variants of RCL1 are associated with a range of neuropsychiatric phenotypes." (PMID 36428813, 2022). "In HER2 positive breast cancer cells, SK-BR3 (black bars), Rpsa and Rcl1 reporter constructs exhibited a strong increase in transactivation of the reporter gene as compared to the empty vector." (PMID 27602772, 2016).
bile duct cancer (1 paper, 2022). "RCL1 was found to be up-regulated in colorectal cancers, but downregulated in liver and bile duct cancers." (PMID 35264160, 2022).
cervical cancer (1 paper, 2019). A primary or metastatic malignant neoplasm involving the cervix. "RCL1 functions in the maturation of 18s RNA and is associated with cervical cancer; one role of the gene in this cancer pathology is thought to involve the regulation of insulin receptors." (PMID 31263560, 2019).
cervical squamous cell carcinoma (1 paper, 2022). A squamous cell carcinoma arising from the cervical epithelium. "However, the RCL1 downregulation was notably correlated with higher grade of Cervical squamous cell carcinoma and endocervical adenocarcinoma and UCEC." (PMID 35264160, 2022).
cholangiocarcinoma (1 paper, 2022). A carcinoma that arises from the intrahepatic biliary tree (intrahepatic cholangiocarcinoma) or from the junction, or adjacent to the junction, of the right and left hepatic ducts (hilar cholangiocarcinoma). "The analyses of the RNA-seq data of 23 malignancies in TCGA suggested that the expression of RCL1 was significantly lower in Cholangiocarcinoma and LIHC compared to the adjacent normal tissues." (PMID 35264160, 2022).
developmental delay (1 paper, 2021). "Copy number loss of RCL1 was associated with developmental delay, intellectual disability, ASD, seizures, and schizophrenia in two separate patient populations at the two medical centers." (PMID 33597717, 2021). "Copy number gain of RCL1 was associated with developmental delay, ASD, schizophrenia, and ADHD." (PMID 33597717, 2021). "While the index case has a 2q13 copy number loss, this patient has developmental delay and a 456,511 bp CNV loss encompassing RCL1 and an additional 2q13 duplication." (PMID 33597717, 2021). "ClinGen does not list any benign gains or losses encompassing RCL1 but lists several pathogenic gains and losses, with phenotypes including developmental delay, low-set ears, abnormal gait, facial abnormalities, ASD, and intellectual disability." (PMID 33597717, 2021). "Two of the youngest patients with copy number losses in RCL1 did not have diagnoses of developmental delay or psychiatric phenotypes, though it was too early in their lives for those phenotypes to be recorded." (PMID 33597717, 2021).
IgA nephropathy (1 paper, 2022). "Compared with normal specimens, TFB2M, DDX27, and RCL1 expressions were significantly down-regulated in IgA nephropathy." (PMID 36246620, 2022). "After integration of above machine learning algorithms, we finally determined TFB2M, DDX27, and RCL1 as characteristic RBPs of IgA nephropathy." (PMID 36246620, 2022). "Especially, DDX27, RCL1, and TFB2M were significantly linked to most immune cell populations and immune checkpoints, indicating that above characteristic RBPs might participate in modulating immune cell infiltrations during IgA nephropathy progression." (PMID 36246620, 2022). "Through integration of three machine learning approaches (LASSO, SVM-RFE, random forest), we finally determined three characteristic RBPs of IgA nephropathy: DDX27, RCL1, and TFB2M." (PMID 36246620, 2022). "However, no studies have reported the roles of DDX27, RCL1, and TFB2M in IgA nephropathy." (PMID 36246620, 2022).
liver cancer (1 paper, 2022). An epithelial or non-epithelial malignant neoplasm that arises from the liver. "Both mRNA and protein expression levels of Rcl1 were generally lower in all liver cancer lines in comparison with L-02 cells." (PMID 35264160, 2022). "The endogenous Rcl1 expression levels were detected in a collection of liver cancer cell lines and L-02 cells." (PMID 35264160, 2022).
pancreatic cancer (1 paper, 2021). "We also found that Notch signaling pathway, pancreatic cancer, RNA degradation, VEGF signaling pathway, and WNT signaling pathway were enriched in the low RCL1 expression group via GSEA." (PMID 34257652, 2021).
primary polycythemia (1 paper, 2023). "The region on chr1 includes RCL1, which has been associated with snout ratio and tail curl as well as JAK2, which contributes to human and canine primary polycythemia." (PMID 37582787, 2023).
psychosis (1 paper, 2021). "Here, we utilize a clinical pipeline for identifying causal genes in Mendelian phenotypes, identifying a premature stop-gain in RCL1 in a patient with very early onset psychosis (VEOP)." (PMID 33597717, 2021). "Taken together, our RNA expression analysis and IHC data demonstrate that RCL1 is likely enriched in neurons during the neonatal and adolescence period, offering a pathological basis for early life psychosis." (PMID 33597717, 2021). "These new findings point towards psychosis in AD sharing some genetic liability with schizophrenia and are consistent with the hypothesis that dysregulation of RCL1 is related to various brain-related illness phenotypes." (PMID 33597717, 2021). "Our screening included cell type RCL1 expression patterns from neonatal life to adulthood and offers a pathological transcriptional timeline that aligns with early developmental processes leading up to the psychosis period." (PMID 33597717, 2021).
schizophrenia (1 paper, 2021). A major psychotic disorder characterized by abnormalities in the perception or expression of reality. "The two probands diagnosed with schizophrenia have a duplication and deletion in the RCL1 gene, respectively." (PMID 33597717, 2021).
Stomach adenocarcinoma (1 paper, 2022). "It was revealed that RCL1 expression was positively correlated to tumor stage in KIRC, LIHC, and Stomach adenocarcinoma, as well as in UVM." (PMID 35264160, 2022).
tumor (6 papers, 2016 to 2025). "The lower expression of RCL1 is associated with higher tumor stage, higher AFP level, vascular invasion, and poor prognosis." (PMID 35264160, 2022). "We examined the relationship between RCL1 expression and immune cells infiltration, tumor mutation burden (TMB), and microsatellite instability (MSI)." (PMID 34257652, 2021). "Notably, it was in LIHC that RCL1 expression was not only significantly down-regulated but also associated with prognosis, tumor progression across many human cancers." (PMID 35264160, 2022). "In summary, these results confirmed that RCL1 could be a potential tumor-associated gene in several malignancies." (PMID 35264160, 2022). "Moreover, the association between RCL1 expression and tumor progression across human cancers was identified." (PMID 35264160, 2022). "And low RCL1 expression was associated with poor prognosis and tumor stage in multiple cancers." (PMID 35264160, 2022). "Besides, bioinformatic analyses indicated that low RCL1 expression was the risk factor of poor survival prognosis and tumor progression, including: advanced TNM classification, high AFP level, vascular invasion in many HCC cohorts." (PMID 35264160, 2022). "CPEB3 has been shown to inhibit the progression of gastrointestinal and hepatic cancers by regulating mRNA translation, whereas RCL1 is suggested to act as a tumor suppressor via ribosome biogenesis modulation." (PMID 40561176, 2025). "The correlation between RCL1 expression and tumor immune infiltration was assessed via the TIMER2.0 database." (PMID 35264160, 2022). "Eleven HCC datasets were downloaded and analyzed to further verify RCL1 expression in HCC tumor tissue." (PMID 35264160, 2022). "It suggested that Rcl1 may play a dualistic role by acting both as an oncogene and tumor suppressor, which is similar to other ribosome biogenesis factors." (PMID 35264160, 2022). "Second, despite in vitro experiments suggested that Rcl1 may be a tumor suppressor in HCC, additional animal tests should be performed." (PMID 35264160, 2022). "Rcl1 may serve as a novel tumor suppressor in HCC, and its biological effect needs further study." (PMID 35264160, 2022). "Our study revealed that Rcl1 may act as a potential prognostic marker and tumor suppressor in HCC." (PMID 35264160, 2022). "Moreover, functional tests indicated Rcl1 may be a potential tumor suppressor in HCC in vitro." (PMID 35264160, 2022). "Meanwhile, we also explored the RCL1 expression level in TCGA by the HCCDB database, and the results showed that the difference in RCLI expression between HCC adjacent normal tissue and tumor tissue was highly significant compared with the other cancers." (PMID 34257652, 2021). "Among those, we identified MCM5, STMN1, RCL1 and C9ORF114, proteins that reflect the high proliferation rate of these tumours." (PMID 26725330, 2016). "Notably, NSUN6 emerged as the most influential protective factor, followed by other tumor‐suppressive genes such as CPEB3, RCL1 and DYRK1A." (PMID 40561176, 2025). "The TN clusters (TN and TN+Her2) include proliferative proteins (MCM3 and 5), translation related proteins (RCL1, MRPS27, EIF2S2 and EEF1G) and metabolic enzymes (glutaminase and hexokinase 2), which reflect the higher dependence on glutamine and glucose of TN versus the other tumours." (PMID 26725330, 2016).
cancer (3 papers, 2019 to 2022). A tumor composed of atypical neoplastic, often pleomorphic cells that invade other tissues. "Low RCL1 expression was remarkably associated with poor prognosis in all these cancer types except for UCEC and UCS." (PMID 35264160, 2022). "We first explored the general expression of Rcl1 in multiple human cancers using the GEPIA2 website portal." (PMID 35264160, 2022). "Interestingly, it was also revealed that there was a marked difference in the distribution of Rcl1 protein between the liver cells and cancer cells." (PMID 35264160, 2022). "Furthermore, the results of cell experiment indicated that Rcl1 plays a pivotal anti-cancer role by inhibiting of both growth and metastasis of HCC." (PMID 35264160, 2022). "RNA 3’-terminal phosphate cyclase-like protein (Rcl1) is involved in pre-rRNA processing, but its implication in cancers remains unclear." (PMID 35264160, 2022).
neurological diseases (2 papers, 2021). "Further researches demonstrated that the expression of RCL1 increases with the development of brain, and RCL1 deletion can cause a variety of neurological diseases." (PMID 34257652, 2021). "Having established the involvement of RCL1 in the brain and behavior of our index VEOP patient, we queried two academic medical centers and confirmed the involvement of RCL1 in 13 additional patients with neurological disorders." (PMID 33597717, 2021).
adenocarcinoma (1 paper, 2022). A common cancer characterized by the presence of malignant glandular cells. "However, RCL1 expression of Colon and Rectum adenocarcinomas were significantly higher than the one in normal tissues." (PMID 35264160, 2022).
infection (1 paper, 2021). The state of being infected such as from the introduction of a foreign agent such as serum, vaccine, antigenic substance or organism. "Sera had PP values of less than one prior to infection for both ES products and rCL1." (PMID 33276290, 2021).
RCL1 also shares sentences with these, for which no sentence is quoted: Alzheimer disease (1 paper); Cirrhosis (1); colorectal cancer (1); dementia (1); endocervical adenocarcinoma (1); fasciolosis (1); glioblastoma multiforme (1); inflammatory bowel disease (1); Intellectual disability (1); ovarian serous cystadenocarcinoma (1); Paranoia (1); Seizure (1); uterine carcinosarcoma (1); uterine corpus endometrial carcinoma (1); uveal melanoma (1).